GLS (glutaminase)
Diseases named in the same sentence as GLS in open-access papers (continued):
Sharing a sentence is not in itself a finding about the gene and the disease.
glioma (continued). "Recent investigations have reported how overexpression of IDH1mut protein in glioma cell lines downregulates TCA cycle intermediates in view of the Gln demand for synthetizing 2HG and have explored the inhibition of GLS as a therapeutic approach against IDH1mut cancers." (PMID 33101674, 2020). "GLS and LDHA are metabolic enzymes that participate in biological progression of IDH-mutant glioma; however, the role of AS of GLS and LDHA in glioma remains unclear." (PMID 31729991, 2019). "This metabolic adaptation may be in line with the increased dependency of IDH1-mutant gliomas on exogenous glutamine, the low levels of glutamate in IDH1-mutant gliomas and the sensitivity of these tumors to glutaminase inhibitors." (PMID 24252742, 2013). "This study suggests that Chr-A markedly reduces the expression levels of GLS, GDH1, HK2 and G6PD in U87 and U251 glioma cells, which support the significant metabolic pathways identified through AFADESI-MSI, suggesting that these key enzymes might be potential targets for Chr-A." (PMID 39330272, 2024). "The different isoforms of glutaminase can meet the metabolic needs of various types of tumors: the reduced expression or enzymatic activity of GLS produces antagonistic effects on lymphoma, glioma, breast, pancreas, non-small cell lung cancers and kidney cancers." (PMID 37627630, 2023). "In addition to the levels of GLS, MTF1, and PDHB, those of the other seven CRGs significantly affected the OS, DSS, and PFI of glioma patients; cuproptosis may play a major role in disease progression." (PMID 36579333, 2022). "Also, SNAP25-knockdown glioma cells (A172 sh-SNAP25 and U118 sh-SNAP25) showed lower GLS expression compared to sh-NC cells and overexpression of SNAP25 witnessed an increased expression of GLS according to the western blot assay (p<0.05)." (PMID 34490096, 2021). "In this study, we brought together our novel inhibitors of enolase, HEX, and POMHEX, as well as the glutaminase inhibitor CB-839, to investigate the redundancies between glycolysis and glutaminolysis for supporting tumor growth and viability in vitro and in vivo in ENO1-deleted gliomas." (PMID 34172075, 2021). "But the exact role of GLS in SNAP25-regulated glioma progression has not been studied." (PMID 34490096, 2021). "Our data indicated that AS of GLS and LDHA were signatures of pST6 and pST7, respectively, the clusters with the best prognosis, suggesting that both expression and AS of metabolic enzymes might be involved in IDH-mutant glioma." (PMID 31729991, 2019). "Therefore, inhibition of glutaminolysis with different glutaminase inhibitors (BPTES, CB-839) has shown higher in vitro anti-leukemic activities in IDH mutant cells than in IDH wild-type cells, in line with the results obtained in gliomas." (PMID 31319822, 2019). "Inhibition of glutaminase, a key enzyme in the conversion of glutamine to glutamate, by BPTES [bis-2-(5-phenylacetamido-1,2,4-thiadiazol-2-yl)ethyl sulfide] and CB-839 has been shown to have anti-proliferative effect in triple negative breast cancer, leukemia and glioma." (PMID 29212209, 2017). "Thus, HOTAIR-miR-126-5p-GLS signaling may have significant effects on multiple aspects of glutamine metabolism, aberrant angiogenesis, cellular invasiveness, and temozolomide resistance (see also “HOTAIR as a Mediator of Chemoresistance in Gliomas” section) in glioma pathophysiology." (PMID 38366205, 2024). "Indeed, treatment of orthotopic xenograft GBM tumors with GLS inhibitors, including the most potent allosteric GLS inhibitor CB‐839, specifically sensitizes IDH‐mutant gliomas and not IDH‐wild type gliomas to radiation treatment." (PMID 38105543, 2025).
hepatocellular carcinoma (59 papers, 2015 to 2026). A malignant tumor that arises from hepatocytes. "Ultimately, synergistic blockade of glutaminolysis and urea cycle indicates that taurine is sufficient to substantially enhance the efficacy of the glutaminase GLS1 inhibitor in management of hepatocellular carcinoma." (PMID 41708583, 2026). "Simultaneous blocking of glutaminase by CB-839, and of Gln import with V-9302, has shown synergistic effects in hepatocellular carcinomas." (PMID 36834787, 2023). "Hepatoma cells contain a large number of glutaminase, which is the initiating enzyme and the key enzyme (rate-limiting enzyme) of tumor cells using glutamine for glutamine yeast." (PMID 38304027, 2023). "GLS2 expression was scarce in hepatocellular carcinomas and glioblastomas, which showed high levels of GLS." (PMID 34573287, 2021). "A series of small molecules with alkyl benzoquinone functional groups decreased the intracellular glutaminase activity in lung, breast, and liver carcinoma cell lines and inhibited GAB more strongly than KGA." (PMID 33746066, 2021). "Previous work has revealed a series of alkyl benzoquinones that inhibit GLS2 more strongly than they do to GLS and decreased intracellular glutaminase activity in lung, breast, and liver carcinoma cell lines." (PMID 33746066, 2021). "Co-expression of GLS and GLS2 transcripts has been reported in established cancer cell lines of colon, hepatoma, leukemia and breast, although protein data suggest that GLS isoforms would account for the majority of GA activity in these human tumor cells." (PMID 32042057, 2020). "It has been reported that gene expression of GDH1 and glutaminase is increased by ammonium in the culture medium of metastatic Hep3B (human hepatoma) cells under normoxia." (PMID 32328457, 2020). "Our previous study demonstrated that the kidney form of glutaminase (GLS1) is highly expressed in hepatocellular carcinoma (HCC) cells and can be used as a target for effective anticancer therapy." (PMID 27835669, 2016). "Moreover, the switching to GLS upregulation in combination with GLS2 repression in hepatoma cells has been found to be accompanied by malignant transformation in an experimental setting." (PMID 28939850, 2017). "The applicability of GLS inhibitors or glutamine depletion against hepatocellular carcinoma (HCC) is still at the preclinical stage, with research showing that hepatoma cells display altered sensitivity associated with self-generated adaptive mechanisms." (PMID 38802351, 2024). "ROS/Wnt/β-catenin signaling has been shown to regulate the stemness in hepatocellular carcinoma (HCC) by targeting glutaminase 1 (GLS1)." (PMID 33968932, 2021). "MiR-122 modulates glutamine (Gln) metabolism both in vitro and in vivo, implicating the therapeutic potential of miR-122 in hepatocellular carcinoma (HCC) that exhibit relatively high GLS levels." (PMID 35082837, 2021). "Ginsenoside Rk1 suppressed ERK/c-Myc signaling, down-regulated glutaminase GLS1, and decreased glutathione production, which stimulates ROS and apoptosis in hepatocellular carcinoma." (PMID 38001865, 2023). "The mRNA expression levels of SLC7A5 and GLS were significantly decreased after treatment with JHU083, which demonstrated the successful inhibition of glutamine metabolism in subcutaneous hepatocellular carcinoma tumor tissue." (PMID 36497182, 2022). "Hypothetically, GLS promoter methylation could be relevant, similar to what occurs in Hepatocellular Carcinoma (HCC), as well as microRNAs-mediated upregulation of gene expression." (PMID 33589573, 2021). "In hepatocellular carcinoma, PTBP1 could promote cisplatin resistance via strengthening glutamine uptake and enhancing glutaminase (GLS) expression." (PMID 38993556, 2024).
hepatocellular carcinoma (continued). "It is noteworthy that, in human hepatocellular carcinoma, GLS2 expression positively correlates with the level of miR-122, which inhibits GLS expression; moreover, Gls2 expression is lower in liver tissues from miR-122 knockout mice compared to wild-type animals." (PMID 38067269, 2023). "Besides, when miR-122 was overexpressed in the glutamine-dependent hepatocellular cancer cell line EC4, the attenuation of glutaminolysis was observed with the suppression of GLS activity, while gluconeogenesis increased." (PMID 32326003, 2020). "Of note, GLS expression does not predict the prognosis of liver cancer based on analysis of two hepatocellular carcinoma cohorts." (PMID 30899051, 2019). "Then, using Liver Hepatocellular Carcinoma database of The Cancer Genome Atlas (TCGA-LIHC), the authors demonstrated an inverse correlation between a high expression of GLS and SLC1A5 with low levels of miR-122 and related this to poor prognosis in high-grade primary HCC tumors." (PMID 32326003, 2020).
lung cancer (53 papers, 2014 to 2026). A malignant neoplasm involving the lung. "HDAC4 deacetylates glutaminase at lysine 311, inhibits K63‐linked ubiquitination of glutaminase, enhances enzyme activity and thus promotes tumourigenesis in non‐small cell lung cancer." (PMID 39778006, 2025). "The inactivation of KEAP1 in KRAS mutations is related to the inhibition of glutaminase in lung cancer." (PMID 32206449, 2020). "Blocking Ser314 phosphorylation by the S314A mutation in lung cancer cells inhibits the glutaminase activity, triggers genetic reprogramming, and alleviates tumor malignancy." (PMID 29515166, 2018). "Therefore, targeting glutaminolysis using glutaminase inhibitors presents a promising therapeutic approach for aggressive subtypes of lung cancer with mutations in KEAP1/NRF2." (PMID 32112372, 2020). "This decreased glutathione levels and subsequent cell death were already demonstrated in lung cancer cells treated with glutaminase inhibitors." (PMID 40943167, 2025). "Targeting glutamine metabolism, particularly through GLS inhibition, represents a potential strategy to enhance radiosensitivity in lung cancer therapy." (PMID 40308578, 2025). "Although STK11/LKB1 mutant lung cancers carry an unfavorable prognosis, the administration of different chemotherapeutic agents that target mTOR, glutaminase, and PD-L1 has shown to increase survival in NSCLC patients." (PMID 35165542, 2022). "For instance, the KEAPSAKE trial (Clinicaltrials.gov; NCT04265534) evaluated addition of a glutaminase inhibitor (telaglenastat) to standard-of-care immunotherapy and chemotherapy in advanced lung cancer." (PMID 35626147, 2022). "In a word, our study showed that FDX1, a key enzyme for cuproptosis, affected the prognosis of lung cancer patients by influencing the expression of GLS, PDHA1, PDHB, DLAT, and MTF1." (PMID 36620594, 2022). "The glutaminase inhibitor CB-839 has been shown to produce an anti-tumor effect in KRAS-mutant lung cancer cells which carry inactivation of the KEAP1 gene resulting in NRF2 hyperactivation and xCT overexpression." (PMID 36338517, 2022). "In lung cancer cells, it was shown that glutaminase inhibition can sensitize the radiation-induced treatment resistance in the Keap1 and Nrf2 mutant cells." (PMID 35945195, 2022). "Recent clinical trials studying the effects of glutaminase inhibitors, mTOR inhibitors, and anti-PD-L1 therapy in lung cancer patients have yielded promising results." (PMID 35165542, 2022). "In this review, we describe that the proliferation and invasion of lung cancer cells can be inhibited by directly targeting molecules in the Gln pathway such as Gln transporters, glutaminase, GFAT, xCT, or enzymes involved in biosynthesis or redox homeostasis." (PMID 35223460, 2021). "Much attention has been paid to the inhibition of GLS in current studies focusing on targeting Gln metabolism in lung cancer patients." (PMID 35223460, 2021). "Inhibition of glutaminolysis, the deamination process of glutamine into glutamate, by targeting glutaminase GLS1 alleviates cancer metastasis by suppressing Snail in lung cancer." (PMID 32509584, 2020). "In a KRAS-mutant lung cancer mouse model, KEAP1 or Nrf2 mutations increased the sensitivity of glutaminase inhibitors." (PMID 32509584, 2020). "KEAP1/NRF2 signalling regulates glutaminolysis metabolism by inhibition of glutaminase in KRAS-KEAP1 mutant lung cancer and regulates the sensitivity to EGFR-TKI." (PMID 33186371, 2020). "CB-839 is a highly potent glutaminase inhibitor that has shown anti-tumor activity in both in vitro and in vivo models of lung cancer." (PMID 32624705, 2020). "Keap1-mutant lung cancer cells have been shown to demonstrate increased sensitivity to GLS inhibition and glutamine deprivation." (PMID 32937954, 2020). "In contrast, whereas GLS demonstrated anti-oncogenic roles in bladder, kidney, and lung cancer, GLS2 acted as a tumor suppressor in brain, kidney, pancreatic, and skin cancer." (PMID 30871151, 2019).
lung cancer (continued). "We treated GLS high (Calu6, H2030) and GLS low (H23, H1299) lung cancer cell lines with the stable isotope 15N-(amide)-glutamine, which liberates 15N-ammonia in the process of glutaminolysis." (PMID 28871132, 2017). "Lung cancer cell lines vary in GLS expression, and therefore represent an excellent model to study glutamine-derived ammonia using this assay." (PMID 28871132, 2017). "We apply this assay to quantitatively measure glutamine-derived ammonia in lung cancer cell lines with differential expression of glutaminase." (PMID 28871132, 2017). "Increased sensitivity to both glutamine deprivation as well as glutaminase inhibition suggests that Keap1 mutant lung cancers depend on glutamine-derived glutamate to support GSH synthesis." (PMID 28967864, 2017). "In summary, glutaminase is a major hot point in the application of Gln metabolic pathway in lung cancer research, and although it has been favored by the majority of researchers, there is still some distance away from practical application in patient diagnosis and treatment." (PMID 35223460, 2021). "In addition, human KRAS‐mutant lung cancer cell lines harboring NF1 mutations (i.e., H2030 and H2347) showed marked sensitivity to glutaminase and PSAT1 inhibition, while those with WT NF1 (i.e., H23, H2009, and H1792) displayed less sensitivity." (PMID 31036704, 2019). "Sensitivity of Kras-driven mouse lung cancer cells to the glutaminase inhibitor CB-839 correlates with glutamine carbon contribution to the TCA cycle, such that tumors derived from these cells in vivo were insensitive to CB-839 while proliferation of the same cells is inhibited in vitro." (PMID 28826492, 2017). "Furthermore, lung cancer cells induced to undergo epithelial to mesenchymal transition (EMT) acquire sensitivity to the GLS inhibitor." (PMID 25502225, 2014). "SMARCA4-mutant lung cancer cells with intact SMARCA2 depend on elevated OXPHOS activity by upregulating the master transcription factor PGC-1a38, whereas ARID1A inactivation in ovarian cancer cells causes reliance on glutamine metabolism through activating glutaminase expression." (PMID 37210563, 2023). "Besides, it was evidenced that high level of GAC phosphorylation is associated with low survival in lung cancer patients, meanwhile blocking Ser314 phosphorylation in lung cancer cells inhibits glutaminase activity and triggers gene reprogramming, subsequently suppressing lung cancer progression." (PMID 35223460, 2021). "By systematically analyzing the genetic alterations of 10 cuproptosis-related genes in lung adenocarcinoma, we found that CDKN2A, DLAT, LIAS, PDHA1, FDX1, GLS, and MTF1 were differentially expressed between lung cancer tissues and adjacent tissues." (PMID 36712848, 2022). "GLS and GLS2 inhibitors were discovered which were able to inhibit cell proliferation in various types of cancer, including breast, blood, and lung cancer." (PMID 30871151, 2019). "In addition to CDKN2A, genes, including DLD, LIPT1, GLS, PDHB, and PDHA1, also have significant CNVs, indicating the heterogeneity of lung cancer tissue." (PMID 36712848, 2022). "THZ1, a covalent inhibitor of cell cycle protein-dependent kinase 7 (CDK7), can alter the expression pattern of glutaminase isoforms by promoting ubiquitination and degradation of NUDT21, ultimately inhibiting the proliferation and migration of lung cancer cell lines." (PMID 35223460, 2021). "Lowering the plasma concentration of glutamine, inhibition of glutamine transport, the development of glutamine-mimetics, and the inhibition of critical enzymes such as GLS and GLUD are interesting pharmacological strategies to inhibit the glutamine metabolism in lung cancer cells." (PMID 30634602, 2019). "Our previous work identified the inhibition of glutaminase as a metabolism-based strategy to combine with CDK4/6 targeting therapy, a combination subsequently corroborated as effective to overcome CDK4/6i resistance in esophageal squamous cell carcinoma and lung cancer." (PMID 40696167, 2025).
lung cancer (continued). "These analyses demonstrated that mRNA expression of G6PD, glutaminase (GLS), hydroxy-prostaglandin dehydrogenase 15-(NAD) [HPGD], TKT, TALDO1, ribulose-5-phosphate-3-epimerase (RPE), and transketolase-like-1 (TKTL1) were more abundant in lung cancer patient samples." (PMID 34827081, 2021). "Thus, targeting GLS could be an effective strategy to block the EMT process, and therefore impair the invasive abilities of aggressive lung cancer cells." (PMID 30634602, 2019). "Indeed, treatment with a selective glutaminase inhibitor CB-83954 strongly suppressed cell viability and proliferation, reduced OXPHOS, and induced apoptosis in SMARCA4/2-deficient ovarian and lung cancer cell lines, but not in proficient controls." (PMID 37210563, 2023).